POMC (proopiomelanocortin)
Diseases named in the same sentence as POMC in open-access papers (continued):
Sharing a sentence is not in itself a finding about the gene and the disease.
Obesity (continued). "This perspective underscores the developmental plasticity and functional versatility of POMC neurons, offering new insights into the mechanisms of obesity and potentially paving the way for novel targeted therapeutic strategies." (PMID 40971005, 2025). "In this context, fluoxetine (FLX) appears to exert its anti-obesity effects by selectively remodeling the synaptic inputs on POMC neurons." (PMID 40130157, 2025). "Seven publications reported outcomes of MBS in patients with obesity caused by rare variants in LEPR, MC4R, NCOA1, PCSK1, POMC, SH2B1, or SIM1." (PMID 40560452, 2025). "Loss-of-function mutations in the genes encoding POMC, MC3R, and MC4R can lead to the dysregulation of energy expenditure and feeding balance, early-onset obesity, and developmental dysregulation." (PMID 40001512, 2025). "For example, circulating peptide leptin stimulates proopiomelanocortin (POMC) and inhibits AgRP neurons in the arcuate nucleus to regulate energy homeostasis, and has been readily associated with obesity." (PMID 40991304, 2025). "The limbic system also receives projections from POMC neurons and neuropeptide-Y neurons in the ARC, the appetite center, and obesity-induced sympathetic nervous system hyperactivity is mediated by POMC-PVN activation." (PMID 39796274, 2025). "Mutations in LEP, LEPR, POMC, and MC4R disrupt this regulatory loop, resulting in hyperphagia, reduced satiety, and early-onset obesity." (PMID 40281302, 2025). "EMANATE aims to extend the indications of setmelanotide beyond biallelic POMC, PCSK1, and LEPR deficiencies, potentially addressing a broader spectrum of genetically driven obesity." (PMID 41212412, 2025). "POMC neurons signal satiety by activating melanocortin receptors, and their dysfunction leads to obesity and insulin resistance." (PMID 40864762, 2025). "Leptin receptor and proopiomelanocortin deficiency are monogenic obesity disorders caused by bi-allelic variants in LEPR and POMC or PCSK1, respectively." (PMID 40564803, 2025). "Loss-of-function mutations in the POMC, MC4R, and MC3R genes cause severe obesity, lowering the length and quality of life of the patients due to complications such as cardiovascular disease, type 2 diabetes, and NAFLD." (PMID 40001512, 2025). "When this particular HDAC is knocked out in ARC POMC neurons, mice become hypersensitive to diet-induced obesity (DIO)." (PMID 40283207, 2025). "The hunger-suppressing action of GLP-1 RAs is thus utilized in obesity treatment, as they affect feeding behavior and induce satiety by modulating POMC neurons." (PMID 40431402, 2025). "In contrast, monogenic obesity, caused by a single, rare mutation in genes like LEP, LEPR, POMC, or MC4R, accounts for less than 1% of obesity cases." (PMID 40564803, 2025). "Key genes implicated in monogenic obesity include those involved in the leptin-melanocortin signaling pathway, such as MC4R, LEPR, PCSK1, and POMC, among others." (PMID 40281302, 2025). "In a high-fat diet (HFD)-induced obesity model, we determined the gene expression levels of agouti-related peptide (AgRP) and pro-opiomelanocortin (POMC) in the hypothalamus." (PMID 39057086, 2024). "In a previous large exome-sequencing study of patients with severe obesity, rare heterozygous variants in SRC1 were detected and were associated with the dysregulation of POMC expression." (PMID 38397265, 2024). "On the other hand, the effects of leptin on glucose homeostasis in the context of obesity and insulin resistance are mediated by POMC-expressing neurons within the hypothalamic arcuate nucleus." (PMID 38707092, 2024). "Patients with SRC1 mutations and severe obesity have been enrolled in phase 2 clinical trials of setmelanotide, an MC4R agonist, approved for obese patients with POMC or LEPR mutations." (PMID 38397265, 2024). "The drug is also indicated for obesity-related to proopiomelanocortin (POMC), proprotein convertase subtilisin/kexin type 1 (PCSK1), or leptin receptor (LEPR) deficiency." (PMID 39211725, 2024).
Obesity (continued). "Rodent models of obesity induced by high-fat diets showed upregulation of Hsp72 (compatible with the Hsp70.1 in humans) in POMC neurons of the arcuate nucleus." (PMID 39683565, 2024). "A role for hypothalamic miRNAs in maintaining energy homeostasis is largely unexplored, but deletion of the miRNA processing enzyme DICER in POMC neurons results in obesity, and hypothalamic miR-29a and miR-103 have been shown to protect against obesity." (PMID 38833481, 2024). "SIK2 suppresses the inflammatory content of the POMC secretome primarily in the early phase of the ER stress response, parallel to its effect on two other groups, including obesity and feeding behavior and axon guidance and neurite outgrowth." (PMID 39329749, 2024). "HFD-induced obesity also affects the metabolic signalling-dependent interplay created by the opposite neuronal regulation of AgRP and POMC neurocircuits." (PMID 38378998, 2024). "Semaglutide treatment restored GLP-1 levels, regulated Socs3 expression in ARC and improved leptin sensitivity and the hypothalamic anorexigenic signaling (POMC/MC4R) for obesity control in these obese mice." (PMID 39728000, 2024). "Activation of POMC neurons suppresses appetite, whilst mTOR signaling in POMC neurons reduces POMC expression and triggers hyperphagia-induced obesity." (PMID 39063184, 2024). "Out of the thirty-three genes for which selected genetic variants were reported as significantly associated with obesity, only four genes (LEP, LEPR, POMC, and MC4R) are known to be linked with monogenic obesity." (PMID 39457458, 2024). "Collectively, these data reveal that p62 acts on POMC or AgRP neurons to promote POMC expression, but inhibits AgRP expression to regulate energy metabolism and prevent obesity." (PMID 39479445, 2024). "It is also important to determine the role of ROS in dietary oil toxicity for inducing POMC neuronal degeneration/death and obesity." (PMID 39683565, 2024). "On the contrary, deletion of PPARγ in POMC neurons in high-fat diet fed mice attenuated hyperphagia, increased energy expenditure, and protected from obesity and leptin resistance." (PMID 39290326, 2024). "The evaluation of deletions and duplications, in regions associated with obesity, is possible by assessing genes LEPR, POMC, SIM1, LEP, MC4R, MC2R, and MC3R, and in the 16p11.2 region by MLPA." (PMID 39458556, 2024). "The hormone leptin’s role in driving anti-obesity effects is well established, by binding to leptin receptors on POMC (anorexigenic) neurons." (PMID 38776045, 2024). "Secreted factors induced microglial priming and promoted chronic inflammation in the hypothalamus, which disrupted energy homeostasis possibly by attenuating POMC neural activity in the early stage of obesity development." (PMID 38317079, 2024). "Evaluation of the prevalence of monogenic forms of obesity in this cohort, with a special focus on leptin–proopiomelanocortin pathway abnormalities, will be investigated in the next stage of this study." (PMID 39407760, 2024). "Mutations inducing loss of function of several genes within this pathway, including mutations in POMC, LepRb, or MC4R genes, have been shown in other in vivo studies to cause early-onset severe obesity." (PMID 38540381, 2024). "Disruption of the hypothalamic circuits controlling body weight and appetite caused by mutations in the genes encoding leptin, LEPR, POMC and MC4R can lead to severe obesity in humans." (PMID 39526054, 2024). "Individuals with obesity and T2D present leptin resistance and higher circulating levels that drastically reduce the signaling of leptin in POMC neurons and the anorexigenic activity in the ARC." (PMID 39728000, 2024). "While many connections are yet to be uncovered to fully comprehend HFD-induced metabolic inflammation within the ARC nucleus, it is evident that this inflammation impacts POMC neurons, leading to obesity." (PMID 38892653, 2024).
Obesity (continued). "Ablation of POMC neurons was reported to result in a mild obesity phenotype characterized by both reduced and increased food intake." (PMID 37443835, 2023). "The incapacity of POMC-C28F mutant to generate functional derivates eventually results in the occurrence of hyperphagia and severe obesity." (PMID 37152279, 2023). "In contrast, for anorexigenic POMC and MC4R neurons, animal models with loss of function develop obesity while those of gain of function have a limited impact on body weight." (PMID 37069175, 2023). "Recently, a new conceptual framework of POMC neuronal heterogeneity integrating with appetite regulation, metabolic physiology and obesity was proposed." (PMID 36819678, 2023). "It has also been shown that SOCS3 knockout mice had improved leptin sensitivity through increased hypothalamic STAT3 phosphorylation and POMC induction, while showing resistance to high-fat diet-induced obesity." (PMID 37571301, 2023). "In POMC neurons in aged mice, an elevation in mTOR activity was observed, which can indirectly lead to POMC neuronal soma enlargement and a decline in the projection of neurites to the paraventricular nucleus (PVN), which causes age-dependent obesity." (PMID 36899905, 2023). "In the ARN, stimulation of GABAB receptor in POMC neurons prevented hypothalamic inflammation, obesity, and insulin resistance in mice." (PMID 37886966, 2023). "DRP1-mediated mitochondrial fission negatively regulates POMC neuronal responses to glucose and leptin sensitivity contributing to obesity and diabetes development." (PMID 37174622, 2023). "The deletion of Mfn2 in the anorectic pro-opiomelanocortin (POMC) neurons of the hypothalamus disrupts endoplasmic reticulum (ER)–mitochondria contacts, ER stress activation, leptin resistance, and obesity." (PMID 36677011, 2023). "In patients with other rare genetic diseases of obesity, such as POMC, proprotein convertase subtilisin/kexin type 1 (PCSK1), or LEPR deficiency, notable impairments in quality of life have been reported." (PMID 36647077, 2023). "Our data confirm a regulatory mechanism of POMC expression during embryogenesis that is critical to our understanding of the pathogenesis of obesity." (PMID 37168577, 2023). "Recent evidence suggests that inflammation of the hypothalamus affects the number of POMC and AGRP neurons and interferes the response to glucose, insulin and leptin, which can lead to obesity caused by HFD." (PMID 37028769, 2023). "Disruption of POMC and the enzyme that cleaves POMC, prohormone convertase 1 (PCSK1), also causes severe obesity with hypopigmentation (due to the loss of MC1R signalling) and cortisol deficiency (due to a lack of ACTH)." (PMID 37661743, 2023). "In mice, POMC-dependent overexpression of the PI3K-Akt-mTOR pathway triggers hyperpolarization of POMC neurons, which results in obesity." (PMID 38003013, 2023). "Potentiation of leptin and insulin signaling in POMC neurons confers protection against diet-induced obesity by increased WAT browning and decreased adiposity." (PMID 37443835, 2023). "In a Turkish study of 105 children with early-onset obesity that screened 41 monogenic obesity genes, around 10.5% of the cases were found to carry genetic variants in the SIM1, POMC, PSCK1, MC4R, and LEPR genes." (PMID 37329217, 2023). "This inhibition reduces the responsiveness of POMC neurons to leptin, ultimately contributing to overeating and the development of obesity." (PMID 38027481, 2023). "Decreased histone acetylation of POMC and increased acetylation of NPY have been linked to obesity following exposure to a high-fat diet." (PMID 37899888, 2023). "Overall, their investigation elucidated that in mature neurons from the POMC lineage, miR-29a can protect against insulin resistance, decreased energy expenditure, hyperphagia, and obesity." (PMID 38003013, 2023).
Obesity (continued). "A previous research on the effect of EGCG on obese mice models also showed that the anti-obesity activity of EGCG was produced through increased POMC expression in the hypothalamus of mice." (PMID 37346971, 2023). "Considering the relatively high prevalence of thyroid disease in women of reproductive age, our results shed some light on how POMC cells might be affected by developmental thyrotoxicosis, with long-term consequences for energy balance regulation and susceptibility or resistance to obesity." (PMID 36581316, 2023). "Setmelanotide is also being developed in other rare genetic disorders associated with obesity including Bardet-Biedl Syndrome, Alström Syndrome, POMC and other MC4R pathway heterozygous deficiency obesities, and POMC epigenetic disorders." (PMID 36767008, 2023). "In sum, deficiency for CerS6 in POMC neurons attenuates the diet-dependent effects on mitochondrial morphology in male mice, increases POMC neuron leptin sensitivity, and improves the insulin-dependent regulation of glucose metabolism in obesity." (PMID 38016943, 2023). "Hypothalamic pro-opiomelanocortin (POMC) neuron development is considered to play an essential role in the development of obesity." (PMID 37168577, 2023). "The disease progression of POMC mutant-driven obesity can be recapitulated in the mice with either ERAD or autophagy deficiency." (PMID 37152279, 2023). "For example, deletion of the transcription factor Tap63 from POMC neurons elicits weight gain and obesity in female mice fed a high‐fat diet and thus abolishes the innate protection offered by oestrogen; there is little effect on weight gain in male mice." (PMID 36117117, 2023). "Sequencing of candidate genes for obesity in Labrador Retriever dogs identified a 14 bp deletion in the POMC gene that has a large effect on body weight, a trait strongly correlated with obesity." (PMID 37368776, 2023). "To examine the potential effects on obesity reversal by α-MSH, we first fed POMC-Cre mice HFD to induce obesity." (PMID 37069175, 2023). "Mechanistic studies revealed that deletion of Rho-kinase 1, a protein kinase involved in cytoskeletal reorganization and neuropeptide release, in both AGRP and POMC neuronal populations resulted in leptin resistance and obesity." (PMID 37443835, 2023). "The SV calls (gain/loss) obtained from CoNVaQ were utilized in regression models for body weight and obesity, which included age, sex, neuter status, the top three principal components, and POMC deletion." (PMID 37799139, 2023). "It is an MC4 receptor agonist developed for the treatment of obesity arising from POMC, proprotein convertase subtilisin/kexin type 1 (PCSK1), or LEPR deficiency." (PMID 37712012, 2023). "Although the melanocortin system is a primary focus for leptin’s anorexigenic action in the hypothalamus, obesity in POMC LepRb −/− mice is only a fraction of that observed after global LepRb depletion." (PMID 37064917, 2023). "POMC-restricted depletion of the miR-29 family resulted in late-onset obesity, fat pad enlargement, and insulin resistance in aged female mice, while in males, it caused mild and transient but significant weight gain." (PMID 38003013, 2023). "IKKβ/NF‐κB activation in htNSCs impaired their multi‐directional differentiating capacity, and contributes to decreased POMC neurons, further aggravating obesity and pre‐diabetes phenotype." (PMID 36042571, 2023). "More recently, acute administration of a long acting GIPR agonist, GIPFA-085, acted via the ARC POMC neurons to suppress feeding and increase lipid utilization, while subchronic administration was shown to reduce body weight in diet-induced obesity mice." (PMID 37443835, 2023). "Here we found that mature neurons originating from the POMC lineage employ miR-29a to protect against insulin resistance obesity, hyperphagia, decreased energy expenditure and obesity." (PMID 35490865, 2022).
Obesity (continued). "Mice with ablated POMC neurons develop hyperphagia and obesity, while the activation of hypothalamic POMC neurons inhibits feeding and body weight gain." (PMID 36120438, 2022). "Compared to the rat model (69%), the canine model (79%) offered a greater degree of genetic similarity in the POMC gene because Labrador retrievers have the highest prevalence of obesity among dog breeds and have similar comorbidities as humans." (PMID 36012526, 2022). "Scientists are investigating new obesity drugs based on the POMC-MCR pathway studies to further illuminate the genetic mechanisms partially responsible for the development of obesity." (PMID 36012526, 2022). "Global deficiency of 5-HTCR develops a late-onset hyperphagic obesity, which is exacerbated by HFD feeding, and is mostly mediated via the POMC neurons." (PMID 35887027, 2022). "Ablation of Dicer, the cytoplasmic ribonuclease type III critical for microRNA maturation, in mature forebrain and ARH neurons or in neurons expressing Cre recombinase under control of the POMC promoter (POMCCre) during development results in obesity." (PMID 35873003, 2022). "Conditional knockout of IFT88 or Kif3A in neonatal POMC-expressing neurons leads to obesity in adult mice." (PMID 36568981, 2022). "Individuals with proopiomelanocortin (POMC) or leptin receptor (LEPR) deficiency are young and experience severe obesity, hyperphagia, and comorbidities, which can impair quality of life (QOL)." (PMID 35123544, 2022). "Patients with pro-opiomelanocortin (POMC) defects generally present with early-onset obesity, hyperphagia, hypopigmentation and adrenocorticotropin (ACTH) deficiency." (PMID 35737586, 2022). "In addition, the prevalence of a specific heterozygous mutation in POMC was significantly higher in patients with early-onset obesity than in normal-weight controls, and heterozygous mutations in POMC may interfere with the effectiveness of bariatric surgeries." (PMID 36277690, 2022). "Here we investigated the role of microglial insulin signaling during health and obesity on the anorexigenic proopiomelanocortin (POMC) neurons, as they have been previously shown to be highly sensitive to a chronic hypercaloric environment." (PMID 35328354, 2022). "Congenital deficiency of proopiomelanocortin, encoded by POMC, results in a syndrome of hypoadrenalism, severe obesity, and altered skin and hair pigmentation." (PMID 35207755, 2022). "In past decades, a large number of GWASs have identified hundreds of genes that are associated with obesity, including FTO, MC4R and POMC, and a few of them have been established as obesity genes before." (PMID 36676030, 2022). "Evidence suggests that the H1Rs and POMC neurons in the hypothalamus significantly contribute to olanzapine-induced obesity." (PMID 35365730, 2022). "Deletion of TRPC5 from POMC neurons also leads to obesity in male mice due to increased energy intake and decreased energy expenditure." (PMID 35887027, 2022). "Deletion of ATF4 from hypothalamic POMC neurons protects mice from obesity, glucose intolerance, and leptin resistance during HFD feeding." (PMID 36188456, 2022). "Additional clinically relevant variants or CNVs in genes related to obesity, such as MC4R, POMC and LEPR, were excluded by exome sequencing and a TruSight One Sequencing panel." (PMID 36536132, 2022). "The aim of the project is to establish the Polish database of severely obese children and adolescents and to evaluate the prevalence of monogenic forms of obesity in this cohort, with a special focus on leptin–proopiomelanocortin pathway abnormalities." (PMID 36479220, 2022). "Further, sustained high-fat diet results in a 25% reduction in POMC cells, suggesting that inflammatory-mediated impaired satiety contributes to obesity." (PMID 35884707, 2022).